XCR1 (X-C motif chemokine receptor 1)
Diseases named in the same sentence as XCR1 in open-access papers (continued):
Sharing a sentence is not in itself a finding about the gene and the disease.
infectious disease (1 paper, 2023). A disorder directly resulting from the presence and activity of a microbial, viral, or parasitic agent in humans. "Given that type I IFN are key regulators of XCR1+ cDC function, it is likely that the observed sex-specific differential resistance to infectious disease is due to both qualitative and quantitative differences in XCR1+ cDC development and function." (PMID 37954617, 2023).
XCR1 also shares sentences with these, for which no sentence is quoted: hepatocellular carcinoma (4 papers); Obesity (4); autoimmune disease (3); colorectal cancer (3); non-alcoholic steatohepatitis (3); Crohn disease (2); gastric cancer (2); glioblastoma (2); liver cancer (2); lung adenocarcinoma (2); nonalcoholic fatty liver disease (2); Anxiety (1); autoimmune thyroid disease (1); breast invasive carcinoma (1); cervical cancer (1); cervical squamous cell carcinoma (1); clear cell renal cell carcinoma (1); colon cancer (1); crescentic glomerulonephritis (1); cyst (1); depression (1); encephalomyelitis (1); endocervical adenocarcinoma (1); esophageal adenocarcinoma (1); esophageal carcinoma (1); esophageal squamous cell carcinoma (1); fibrosarcoma (1); glaucoma (1); glomerulosclerosis (1); head and neck squamous cell carcinoma (1).
A further 25 diseases each share a sentence with XCR1 in 1 paper.